INS (insulin)
Diseases named in the same sentence as INS in open-access papers (continued):
Sharing a sentence is not in itself a finding about the gene and the disease.
Insulin resistance (continued). "QDot multicolor cellular imaging demonstrated that amygdalin and cinnamic acid selectively acted via the JNK1-dependent pathway to suppress the inflammation-induced insulin resistance and improve insulin sensitivity." (PMID 25623542, 2015). "Insulin alone showed a high accuracy for defining insulin resistance in this range of values whereas glucose played a minor role in the HOMA-IR variation." (PMID 26241903, 2015). "In regard to assessing the insulin targeting function, we measured the insulin resistance values in experimental and the corresponding control mice." (PMID 26161865, 2015). "TNF-α attenuated insulin-mediated modifications of cell function and metabolism, demonstrating the importance of this cytokine in linking adipose tissue inflammation with insulin resistance." (PMID 26257839, 2015). "HOMA IR is a fasting insulin resistance index that is related with liver insulin resistance, on the contrary, Matsuda Index is an insulin sensitivity index that calculate in an indirect way the insulin sensitivity in muscle after a glucose load." (PMID 25780389, 2015). "These transgenic mice overexpressing IGF-II in β-cells were hyperinsulinemic early in life and showed altered glucose and insulin tolerance tests, as well as insulin resistance." (PMID 26448747, 2015). "Hyperglycemia and insulin resistance in ZDF contribute to increased FFA mobilization and dyslipidemia, which correlate with CV risk in type-2 DM that can be reduced with insulin sensitizers." (PMID 25996498, 2015). "Due to its ubiquity in the insulin-targeted tissues and its reported role in insulin resistance development, inhibiting PTP1B activity would be beneficial in treating T2DM." (PMID 26308010, 2015). "According to the results obtained in the course of GTT (on the 147th day) and IGTT (on the 140th day), the rats of the Group D0 had impaired glucose tolerance, insulin resistance, and significantly decreased insulin-induced glucose utilization." (PMID 26124826, 2015). "The activation of inflammatory signaling can trigger whole-body insulin resistance by directly influencing insulin signaling." (PMID 26308623, 2015). "We found significant correlations between serum adiponectin and fasting serum insulin levels and/or HOMA-IR as parameters associated with insulin resistance, especially in Group 1 female children and in most Group 2 male and female children." (PMID 25904939, 2015). "Collectively, these data suggest that obesity-induced insulin resistance and/or impaired insulin signaling can contribute to AD neuropathology although additional factors also play significant roles." (PMID 26217222, 2015). "Increasing evidence implicates skeletal muscle as a major contributor to the development of insulin resistance, as muscle is the most abundant insulin-sensitive tissue in the body." (PMID 25789156, 2015). "When TNF-α was neutralised, insulin sensitivity was improved, linking adipose tissue inflammation with insulin resistance." (PMID 26693205, 2015). "Insulin resistance and abnormal insulin secretion are the most important prerequisites for the occurrence of type 2 diabetes." (PMID 25664814, 2015). "Conversely, the Matsuda index highly correlates with whole-body insulin sensitivity, as determined by the euglycemic insulin clamp technique, which is the gold standard for measuring insulin resistance." (PMID 25615826, 2015). "Insulin resistance and Type 2 diabetes are marked by an aberrant response in the insulin signaling network." (PMID 26465754, 2015). "In a cultured hepatocytes model, significant insulin resistance was developed under prolonged exposure to insulin, and this is similar to the setting of insulin therapy." (PMID 26276522, 2015). "The aim of this study was to investigate the relationship between dietary insulin load (DIL) and insulin index (DII) and the risk of insulin resistance in Tehranian adults." (PMID 27446819, 2015).
Insulin resistance (continued). "Significant elevation of serum insulin and insulin resistance (HOMA/IR) were observed in obese children too." (PMID 27275288, 2015). "Insulin resistance reduces glucose tolerance especially in muscle cells and adipocytes, where glucose uptake is insulin dependent." (PMID 26640706, 2015). "Experiments performed in rodent models of acute and prolonged (2 weeks) sleep fragmentation confirmed increased adiposity, insulin resistance, hyperglycemia and impaired insulin secretion." (PMID 25834642, 2015). "Once macrophages home to the inflamed fat mass, circulating and tissue proinflammatory cytokines increase, which will inhibit insulin signalling in peripheral tissues, leading to obesity-related insulin resistance." (PMID 25759846, 2015). "EBN however is able to prevent insulin resistance by preventing some of the transcriptional changes on insulin signaling genes induced by HFD." (PMID 26273674, 2015). "Meanwhile, the level of adiponectin (another adipocytokine) was negatively correlated with insulin resistance (fasting insulin level and HOMA-IR), lipid profiles (LDL-c and TG levels), and inflammatory markers (MCP-1 and PAI-1 levels)." (PMID 26011530, 2015). "Since these results suggest that AMPD1 deficiency inhibits the attenuation of insulin signaling in skeletal muscle under high fat diet feeding, they support the notion that AMPD1 deficiency attenuates insulin resistance induced by high fat diet feeding." (PMID 25887856, 2015). "Body fat was estimated by calculating body mass indices (BMI); body fat distribution by waist-hip ratios (WHR); and fasting plasma glucose and insulin levels were used to calculate insulin resistance using the Homeostasis Model (HOMA-IR)." (PMID 25973404, 2015). "Several studies have reported the favorable effect of leucine supplementation on insulin resistance or insulin sensitivity." (PMID 26115673, 2015). "In the context of insulin resistance, insulin dependent cells, such as muscle and fat, have less glucose transferred across their cell membranes per given amount of circulating insulin, so that plasma glucose levels rise." (PMID 25878903, 2015). "Type 2 diabetes is a multifactorial disease characterized by impaired insulin secretion and insulin resistance." (PMID 26218657, 2015). "The optimal conditions for inducing insulin resistance in endothelial cells were a combination treatment of 10−4 mmol/l insulin, 30 mM glucose and 1 μM dexamethasone for 48 h." (PMID 25663871, 2015). "For example, HFD/HFD F1 males demonstrated increased fasted sera glucose concentration and a synergistic increase in sera insulin concentrations, concomitant with insulin resistance (lower AAC for ITT) at both 12/18 weeks of age compared to HFD/CD F1 males." (PMID 25804263, 2015). "Studies have shown a reduction in the number of large-sized adipocytes and an increase in the number of small-sized adipocytes in adipose tissue is correlated to improved insulin sensitivity and reduced obesity-induced insulin resistance." (PMID 26618193, 2015). "Aldosterone plays a positive role to enhance insulin levels, as well as to induce insulin resistance." (PMID 26500555, 2015). "Direct and paracrine signals issued from M1 macrophages can impair insulin signaling and adipogenesis in adipocytes whereas M2 macrophages seem to protect against obesity-induced insulin resistance." (PMID 26565966, 2015). "The present study demonstrated that upregulation of endogenous Ang II-induced ROS impaired insulin signaling and Glut-4 translocation in the skeletal muscle of hypertensive rats and resulted in systemic insulin resistance." (PMID 25928697, 2015). "Glucocorticoids induce hyperglycaemia by inhibiting insulin release and increasing peripheral insulin resistance." (PMID 25755880, 2015).
Insulin resistance (continued). "To exclude weight reduction as a potential confounding factor in insulin resistance, we next evaluated insulin induced phosphorylation of AKT (pAKT) in primary hepatocytes isolated from mice on a chow fed diet." (PMID 25933096, 2015). "Insulin resistance is defined as defective insulin signalling and decreased insulin efficiency to induce glucose transport from the blood into key target cells." (PMID 25652009, 2015). "A prior study in type 2 diabetes patients showed that decreased plasma adiponectin correlated with impaired insulin-stimulated nitric-oxide synthase activity and severity of insulin resistance." (PMID 25705909, 2015). "Insulin resistance assessed by fasting glucose/ insulin ratio (GIR), homeostatic model assessment of insulin resistance (HOMA-IR) or quantitative insulin sensitivity check index (QUICKI) is a well recognised metabolic disturbance of PCOS." (PMID 26645811, 2015). "Perhexiline has the potential to improve insulin sensitivity and treat type 2 diabetes because inhibition of carnitine palmitoyltransferase-1 activity was reported to alleviate insulin resistance in diet-induced obese mice." (PMID 25946000, 2015). "Resistin, on the other hand, impairs cellular glucose intake, because it is stimulated by insulin; as a result, hepatic glucose production is increased, leading to impaired glucose tolerance and eventual development of insulin resistance." (PMID 26273677, 2015). "Taken together, these data link hyperinsulinemia, hepatic fat accumulation, and hepatic insulin resistance and suggest that increased insulin levels promote hepatic fat accumulation and thus hepatic insulin resistance." (PMID 26085100, 2015). "An important key factor in the pathogenesis of metabolic syndrome is insulin resistance, a whole-body decrease in the ability of insulin to stimulate the use of glucose by muscles and adipose tissue and to suppress glucose production in the liver." (PMID 26307979, 2015). "In animal models of insulin resistance, Zinc supplementation is known to enhance insulin sensitivity and antioxidant status." (PMID 26381880, 2015). "The FR_Adlib group had significantly higher glucose, insulin, insulin resistance (assessed by HOMA-IR) and total cholesterol levels than the Adlib_Adlib group." (PMID 25738800, 2015). "Insulin was add-on with metformin to maintain glycemic control when insulin resistance increases in pregnancy that is around 26–28 weeks of pregnancy." (PMID 25874236, 2015). "In a feed forward cycle, the ligand-RAGE signaling results in the up-regulation of RAGE along with the proinflammatory mediators, viz., IL-1β and TNF-α to promote the development of insulin resistance by disturbing insulin signaling." (PMID 25679220, 2015). "Using cultured 3T3-L1 adipocytes, Houstis and colleagues showed that ROS production preceded insulin resistance and ROS scavenging rescues insulin sensitivity." (PMID 25909991, 2015). "Adipose tissue insulin resistance index (Adipo-IR) has been developed to evaluate the degree of antilipolytic effect of insulin." (PMID 26580649, 2015). "This pathophysiological condition, mostly due to insulin resistance, is characterized by the failure of peripheral tissues to respond to the action of insulin, eventually resulting in reduced glycogen synthesis and storage in liver cells." (PMID 26703529, 2015). "It has to be acknowledged that some studies defined insulin resistance on the basis of fasting insulin values or insulin sensitivity indices." (PMID 25663838, 2015). "Insulin resistance which reflects the inability of insulin to properly regulate glucose metabolism is common in people with obesity and/or type 2 diabetes." (PMID 26103456, 2015). "Increased insulin, as well as higher level of glucose, are observed in gestational diabetes mellitus, possibly as a result of the progressively increasing insulin resistance in pregnancy." (PMID 26610599, 2015).
Insulin resistance (continued). "In this study, an elevation of fasting serum insulin level and insulin resistance in NAFLD subjects, in comparison to the controls, supports the latter suggestion." (PMID 26569494, 2015). "Under the label of insulin resistance is a wide range of abnormalities from inappropriate secretions to decreased insulin sensitivity." (PMID 26202599, 2015). "AMP-activated protein kinase (AMPK) plays an important role in insulin resistance, which is characterized by the impairment of the insulin-Akt signaling pathway." (PMID 26266809, 2015). "Insulin resistance manifests reduced insulin sensitivity of peripheral tissue with an abnormality in the insulin signaling pathway, including IRS and other downstream molecules." (PMID 26504484, 2015). "Lipoprotein lipase activity is insulin-dependent and insulin resistance among smokers was observed in many studies." (PMID 26068452, 2015). "Taken together, these data suggest that gut microbe-derived EVs promoted by an HFD can induce T2D via the induction of insulin resistance in insulin-responsive organs." (PMID 26510393, 2015). "As a consequence, an imbalance between reactive molecular species and antioxidant defences was observed in the development of insulin resistance, impaired insulin secretion and during late complications of diabetes." (PMID 26288372, 2015). "Pro-inflammatory cytokines like IL-1β induces apoptosis in insulin-producing β-cells while CCL2 and TNFα are known to impair insulin signalling, and therefore causing insulin resistance." (PMID 27030821, 2015). "By the end of an ad libitum feeding trial these differences were markedly increased, with obese offspring exhibited increased insulin resistance and a decrease in first-phase insulin secretion compared to control offspring." (PMID 25875659, 2015). "NASH females were slightly older and exhibited increased levels of AST, ALT and fasting insulin, and insulin resistance per HOMA2-IR, but these results were adjusted for age." (PMID 26599819, 2015). "Associations of T2D risk alleles with increased fasting insulin and HOMA-IR implicate GRB14 variants playing a role in insulin resistance." (PMID 26363598, 2015). "Intraperitoneal glucose and insulin tolerance tests revealed that 14-3-3ζKO mice were mildly glucose intolerant and exhibited mild systemic insulin resistance." (PMID 26220403, 2015). "Elevated levels of amino acids interfere with normal glucose metabolism, particularly in individuals with reduced insulin sensitivity, leading to insulin resistance." (PMID 25710041, 2015). "Studying multiple cohorts of mice at different time points, we detected consistent modest protective effects of Cx3cr1-/- on diet induced insulin resistance mediated partly through preservation of hepatic insulin sensitivity and signaling." (PMID 26393344, 2015). "The insulin resistance index calculated by the HOMA model (HOMA-IR) using the level of fasting insulin (μIU/mL) and glucose level (mmol/L) indicated that all diabetic rats started the study with significantly higher HOMA-IR values compared to the control rats." (PMID 25838947, 2015). "Insulin resistance refers to impaired or failed cell response to insulin receptor-activated signalling in insulin-sensitive tissues such as the liver, skeletal muscle, adipose, and brain." (PMID 26693205, 2015). "It is well known that skeletal muscle in the dominant position of insulin-mediated uptake plays an important role in the pathogenesis of insulin resistance and is responsible for more than 80% of insulin-stimulated whole body glucose disposal." (PMID 25888350, 2015). "By identifying signal transduction as a contributing factor to individual differences in insulin response, our findings offer an opportunity to tailor pharmacologic correction of insulin resistance." (PMID 26202599, 2015). "Type 2 diabetes is a metabolic disorder characterized by insulin resistance in adipose tissue, liver and skeletal muscle, and defective pancreatic insulin secretion." (PMID 26300887, 2015).
Insulin resistance (continued). "Before the onset of type 2 diabetes, the concentrations of insulin in the plasma increase as a result of insulin resistance." (PMID 25798199, 2015). "Insulin resistance is known showing a reduced insulin sensitivity of peripheral tissue with aberrant IRS-2 and downstream members of the insulin signaling pathway." (PMID 26504484, 2015). "The problem of the effects of the two different types of insulin resistance on insulin secretion has been tackled in different studies." (PMID 26555895, 2015). "A 2-year follow-up cohort study on kidney transplant patients found that blood insulin levels in NODAT were significantly elevated and insulin resistance was the primary cause of TAC-induced NODAT." (PMID 26599323, 2015). "Homeostasis model assessment (HOMA) 2 was calculated to estimate steady-state beta-cell function, insulin sensitivity, and insulin resistance." (PMID 26185508, 2015). "In the correlation analysis, BMI percentile was positively correlated with insulin resistance (fasting insulin level and HOMA-IR) and inflammatory markers (hs-CRP, MCP-1, TNF-α, PAI-1, and leptin levels) but negatively correlated with the adiponectin level." (PMID 26011530, 2015). "GDM and type 2 patients are often overweight and obese, many morbidly obese, characterized by insulin resistance and, therefore, require much larger insulin doses (1–2 units/kg)." (PMID 27057336, 2015). "This occurs because increased insulin secretion can initially compensate for the developing insulin resistance." (PMID 25713323, 2015). "For that purpose, we used a previous tested model of obesity and insulin resistance, and an anti-inflammatory and insulin sensitizing treatment." (PMID 25834641, 2015). "Type II diabetes mellitus is a metabolic disorder of deranged fat, protein and carbohydrate metabolism resulting in hyperglycaemia from insulin resistance and inadequate insulin secretion." (PMID 25848817, 2015). "While DM type 2 patients, as consequence of insulin resistance, usually show normal or higher level of insulin." (PMID 26576637, 2015). "Immunosuppressive drugs contribute to the development of NODAT through different mechanisms including insulin resistance (by corticosteroids), and decrease in insulin secretion (mainly by tacrolimus)." (PMID 25737773, 2015). "It is characterized by progressive insulin resistance in insulin responsive tissues, dyslipidaemia, abdominal obesity, and rise in pro-coagulant and pro-inflammatory factors." (PMID 26300908, 2015). "Type 2 diabetes is a metabolic disorder characterized by a decline in insulin secretion and insulin resistance." (PMID 25699116, 2015). "The definition of insulin resistance implies a lower sensitivity to insulin by cells and alterations on glucose metabolism (for example: uptake or storage)." (PMID 26869866, 2015). "Insulin resistance is defined as an impaired biological response to insulin; however there is sufficient variability in normal sensitivity to insulin that there is no distinct value at which resistance starts and sensitivity ends." (PMID 25834745, 2015). "The strength of the associations between the SLC22A11 and LRRC16A loci was not affected by the serum uric acid levels or other confounders, which suggests a greater likelihood of a direct effect on insulin secretion and insulin resistance." (PMID 25617895, 2015). "A large multinational study involving 17 European and 2 American sites noted a 23 % prevalence of insulin resistance based on insulin clamp, similar to our classification of the top 25 % of our population as insulin resistant." (PMID 27525252, 2015). "In general, insulin resistance occurs when a certain concentration of insulin cannot effectively stimulate glucose uptake and utilization in the peripheral target organs." (PMID 26843885, 2015). "TNFα treatment caused insulin resistance as indicated by a 44% reduction in insulin-stimulated 2DOG uptake, loss of GLUT4 (−48%), and reduced insulin-regulated AKT phosphorylation (−54%)." (PMID 26240143, 2015).